KLHL15 (kelch like family member 15)
Description:
Substrate-specific adapter for CUL3 E3 ubiquitin-protein ligase complex. Acts as an adapter for CUL3 to target the serine/threonine-protein phosphatase 2A (PP2A) subunit PPP2R5B for ubiquitination and subsequent proteasomal degradation, thus promoting exchange with other regulatory subunits. Acts as an adapter for CUL3 to target the DNA-end resection factor RBBP8/CtIP for ubiquitination and subsequent proteasomal degradation. Through the regulation of RBBP8/CtIP protein turnover, plays a key role in DNA damage response, favoring DNA double-strand repair through error-prone non-homologous end joining (NHEJ) over error-free, RBBP8-mediated homologous recombination (HR).
Synonyms: KIAA1677; HEL-S-305; XLID103
Tractability: Small molecule: it belongs to a druggable protein family. PROTAC: ubiquitination databases record sites on it.
Gene: Protein-coding gene on chromosome X (23,983,716 to 24,027,186, reverse strand). Ensembl gene ENSG00000174010.
Subcellular location: Nucleus
Subcellular location (Human Protein Atlas): Cytosol; Aggresome
Gene Ontology:
Molecular function: protein binding; ubiquitin-like ligase-substrate adaptor activity
Biological process: negative regulation of double-strand break repair via homologous recombination; nuclear protein quality control by the ubiquitin-proteasome system; ubiquitin-dependent protein catabolic process; proteasome-mediated ubiquitin-dependent protein catabolic process; protein ubiquitination
Cellular component: Cul3-RING ubiquitin ligase complex; nucleus
Homologues: Orthologues: chimpanzee KLHL15 (99% identical), mouse Klhl15 (99% identical), rat Klhl15 (99% identical), guinea pig KLHL15 (99% identical), dog KLHL15 (99% identical), pig KLHL15 (99% identical), rabbit KLHL15 (99% identical), macaque KLHL15 (97% identical), tropical clawed frog klhl15 (91% identical), zebrafish klhl15 (85% identical). Paralogues in human: KLHL9 (29% identical), KLHL13 (28% identical), KLHL32 (28% identical), KLHL26 (27% identical), KLHL22 (27% identical), KLHL14 (26% identical), KLHL34 (25% identical), KLHL36 (25% identical), KLHL12 (23% identical), KLHL20 (23% identical), KLHL5 (23% identical), KLHL31 (22% identical), and 42 more.
Diseases named in the same sentence as KLHL15 in open-access papers:
KLHL15 is named in the same sentence as 10 diseases in open-access papers, as found by Europe PMC text mining. Sharing a sentence is not in itself a finding about the gene and the disease. The quoted sentences say what the papers report.
Intellectual disability (4 papers, 2016 to 2023). "Considering the available literature and our case, it is evident that XLID associated with KLHL15 involves intellectual disability, mild facial abnormalities, and potential hypogonadism." (PMID 37452054, 2023). "Patients with nonsense variants in KLHL15 may develop intellectual disabilities, minor skeletal anomalies, and facial dysmorphisms." (PMID 37452054, 2023). "Although patients with variants of KLHL15 may develop intellectual disabilities, minor skeletal anomalies, and facial dysmorphism, few case reports have described the clinical manifestations of those patients." (PMID 37452054, 2023). "Recent studies have identified KLHL15 as an X-linked intellectual disability (XLID) gene." (PMID 33199366, 2021). "Interestingly, KLHL15 was most recently identified as a potential X-linked intellectual disability (ID) gene." (PMID 27087860, 2016). "For instance, a patient with a large deletion of 22 kb, including exon 3 of KLHL15, exhibited severe intellectual disability, epilepsy, and anomalies in cortical development." (PMID 37452054, 2023). "Because of KLHL15’s link to severe intellectual disability and its ranking as one of the most clinically significant X-linked disease genes, we set out to uncover novel neuronal substrates of the E3 ubiquitin ligase by primary and secondary structure searches." (PMID 33199366, 2021).
Dandy-Walker malformation (1 paper, 2016). "Furthermore, our data suggests the involvement of CNTN6 and KLHL15 in the etiology of agenesis of the corpus callosum, the involvement of RASD1 and PTPRD in Dandy-Walker malformation, and the involvement of ERMARD in ventriculomegaly." (PMID 27087860, 2016).
cancer (2 papers, 2016 to 2021). A tumor composed of atypical neoplastic, often pleomorphic cells that invade other tissues. "The kelch-like family member 15 (KLHL15) can encode a member of the kelch-like family of proteins and is involved in protein ubiquitination and cytoskeletal organization, but few studies focus on cancers." (PMID 33968141, 2021). "For example, high KLHL15 protein levels may render cancer cells hypersensitive to DNA topoisomerase inhibitors." (PMID 27561354, 2016). "Lastly, our findings may have important therapeutic implications for some cancer types displaying KLHL15 overexpression." (PMID 27561354, 2016).
neurodevelopmental disorder (1 paper, 2021). A behavioral and cognitive disorder with onset during the developmental period that involves impaired or aberrant development of intellectual, motor, or social functions. "Our study uncovers a novel role of the E3 ubiquitin ligase adaptor KLHL15 as a negative regulator of DCX protein abundance and dendritogenesis and suggests possible mechanistic connections in X-linked neurodevelopmental disorders." (PMID 33199366, 2021). "Further studies involving animal models are required to investigate the interplay between KLHL15 and DCX proteins in the pathogenesis of neurodevelopmental disorders." (PMID 33199366, 2021).
KLHL15 also shares sentences with these, for which no sentence is quoted: X-linked intellectual disability (2 papers); epilepsy (1); Hypoglycemia (1); leukemia (1); tumor (1); Ventriculomegaly (1).